MIR4721 (microRNA 4721)
Synonyms: hsa-mir-4721
Gene: MicroRNA gene on chromosome 16 (28,843,919 to 28,844,007, reverse strand). Ensembl gene ENSG00000283845.
Diseases named in the same sentence as MIR4721 in open-access papers:
MIR4721 is named in the same sentence as 1 disease in open-access papers, as found by Europe PMC text mining. Sharing a sentence is not in itself a finding about the gene and the disease.
MIR4721 shares sentences with these, for which no sentence is quoted: Obesity (1 paper).